TOX (thymocyte selection associated high mobility group box)
Diseases named in the same sentence as TOX in open-access papers (continued):
Sharing a sentence is not in itself a finding about the gene and the disease.
infection (19 papers, 2017 to 2025). The state of being infected such as from the introduction of a foreign agent such as serum, vaccine, antigenic substance or organism. "Similarly, P14 T cells expressed more TOX in MOG-GP than WT mice at 21 days after i.c. infection which was associated with an elevated expression of PD-1, TIGIT, LAG-3 but not TIM-3." (PMID 33579927, 2021). "Expression of PD-1, LAG-3, TOX, and Eomes was assessed in P14 cells recovered from the spleens of infected animals ∼30 d after infection." (PMID 34882194, 2022). "After high-dose Ad-HBV-Luc infection, we also detected HBV-specific CD8 T cells with elevated levels of PD1, TIGIT and TOX, markers associated with T cell dysfunction." (PMID 34835079, 2021). "In contrast, TOX expression during rLCMV Clone-13 wt infection was most highly upregulated by Th1 effectors." (PMID 33684030, 2021). "However, after Cl13 challenge infection, we observed high expression of TOX, which was then comparable in the progeny of all transferred cell fractions." (PMID 41488650, 2025). "After primary infection, we found a mild increase in TOX expression in T-betLow cells." (PMID 41488650, 2025). "To determine if TOX deficiency alters stimulation-induced PD-1 upregulation, we cultured MACS-isolated T cells from WT and Tox–/– P14 memory mice (28 days after LCMV Armstrong infection) in the presence of mock, IL-12/15/18, or TCR stimulation." (PMID 34032638, 2021). "Moreover, the module E of greater accessibility occurring at day 21 post infection contains ChARs adjacent to the genes encoding for IRF4 and TOX, two well-known TFs driving T-cell exhaustion." (PMID 33579927, 2021). "Furthermore, at day 5 post-infection, IFNAR1-deficient CD8+ P14 T cells continued to exhibit reduced Ezh2 expression, along with reduced expression of exhaustion-associated molecules, including PD1, TIM3, and TOX, compared to control cells." (PMID 36716323, 2023). "Cells expressing increased levels of PD-1 and TOX can also be found among CD8+ T cells specific to the LCMV-derived np396 epitope at days 15 and 30 after infection." (PMID 39778709, 2025). "The observation of TOX in memory T cells is reminiscent of findings from an earlier analysis of T cell gene coexpression networks in resolving LCMV Armstrong infection and in chronic LCMV clone 13 infection." (PMID 40746547, 2025). "Importantly, TOX and TCF-1 were insufficient to establish and sustain Hmgb2−/− Tex cells throughout Cl13 infection." (PMID 37704621, 2023). "Our RNA-seq data indicated that expression of the gene encoding for TCF-1 (Tcf7) was nearly ablated in absence of TOX in self-reactive CD8+ T cells and, to a lesser extent, in CD8+ T cells that formed 3 weeks after the resolved infection with rLCMV-GP33." (PMID 33579927, 2021). "In addition, we found that TOX expression was higher in the memory-like TCF-1hi subset, a trend which was already noticeable 7 days after infection of MOG-GP mice." (PMID 33579927, 2021). "In summary, the experiments in the late chronic phase showed that a very long infection period can indeed lead to an accumulation of dysfunctional CD8+ T cells, which are characterized by a high degree of co-expression of the co-inhibitory molecule PD-1 and the transcription factor TOX." (PMID 35720419, 2022). "We did not see evidence for TOX downregulating CD8 T cell effector function in the transcription factor network analysis, indicating that TOX may not be involved in the loss of CD8 T cell function during infection with hepatotropic viruses." (PMID 38987588, 2024). "Moreover, TOX and hypoxia inducible factor 1 subunit alpha (HIF-1α) are the key transcriptional regulators in the epigenetic depletion of T lymphocytes post curing of HCV-specific infections; these probably maintain exhaustion leading to the establishment of epigenetic scars." (PMID 36969216, 2023).
hematological malignancies (4 papers, 2021 to 2022). "We also discussed the potential role of TOX as an immune biomarker and target in immunotherapy for hematological malignancies." (PMID 33743809, 2021). "In addition, we previously reported higher expression of immune inhibitory proteins including PD-1, Tim-3, and TOX in Tregs in hematologic malignancies that negatively impact T cell immunosuppressive functions." (PMID 36439426, 2022). "In contrast, there are few studies on TOX genes in hematological malignancies." (PMID 34692519, 2021). "However, little is known about the role of TOX genes in hematological malignancies." (PMID 34692519, 2021). "Overall, TOX and TOX2 might be potential immune biomarkers and targets for hematological malignancy immunotherapy." (PMID 33743809, 2021).
TOX also shares sentences with these, for which no sentence is quoted: T-cell acute lymphoblastic leukemia (4 papers); leukemia (3); liver cancer (3); metabolic syndrome (3); bladder transitional cell carcinoma (2); breast invasive carcinoma (2); classic Hodgkin lymphoma (2); colon cancer (2); diabetes (2); gastric cancer (2); multiple myeloma (2); skin cutaneous melanoma (2); T-lymphoblastic lymphoma (2); -cell proliferations (1); acute respiratory distress syndrome (1); anaplastic large cell lymphoma (1); asthma (1); Astigmatism (1); autoimmune disease (1); brain astrocytoma (1); brain glioma (1); chronic hepatitis (1); colon adenocarcinoma (1); common variable immunodeficiency (1); esophageal carcinoma (1); head and neck cancer (1); HIV-1 infection (1); infectious disease (1); influenza (1); kidney chromophobe (1).
A further 23 diseases each share a sentence with TOX in 1 paper.